TRIM28 (tripartite motif containing 28)
Diseases named in the same sentence as TRIM28 in open-access papers (continued):
Sharing a sentence is not in itself a finding about the gene and the disease.
prostate carcinoma (continued). "However, TRIM28 cistrome and regulation of gene expression in PCa cells remain to be studied, despite a recently study suggesting TRIM28 enrichment at tumor-specific closed chromatin in prostate cancer cells." (PMID 30479348, 2018). "In prostate cancer, NSUN2 adds m5C modifications to TRIM28 mRNA, increasing its stability and promoting TRIM28 protein expression." (PMID 41256859, 2025). "The interaction between TRIM28 and TRIM24 protects TRIM24 from SPOP-mediated ubiquitin degradation and promotes the progression of prostate cancer." (PMID 34330324, 2021). "TRIM28 prevented TRIM24 from SPOP-mediated degradation, promoting the progression of prostate cancer." (PMID 34722282, 2021). "In prostate cancer, as a key upstream regulator of TRIM24, TRIM28 was proved to interact with TRIM24 to prevent its ubiquitination and degradation by SPOP and also enhance the signal transduction of Androgen receptor (AR)." (PMID 33817325, 2021). "Previous studies have shown that TRIM28 protects TRIM24 from SPOP-mediated ubiquitin degradation and promotes the progression of prostate cancer." (PMID 34330324, 2021). "Here, the authors show that TRIM28 interacts with TRIM24 to prevent SPOP-mediated ubiquitination of TRIM24 and enhances TRIM24 and AR signaling to induce prostate cancer tumorigenesis." (PMID 30479348, 2018). "Amongst these sets, the novel candidates KAT2A, TRIM28 and HEY1 are particularly interesting, as they represent previously unknown putative drivers of prostate cancer." (PMID 28592290, 2017). "Of the highlighted genes without previously known roles in prostate cancer, we find it interesting to note that both KAT2A and TRIM28 have epigenetic remodelling functions." (PMID 28592290, 2017).
glioblastoma (17 papers, 2014 to 2026). The most malignant astrocytic tumor (WHO grade IV). "In Glioblastoma (GB), TRIM28 was also overexpressed in tumor stem cells and associated with the expression of stem cell-related genes." (PMID 36756159, 2023). "Additionally, TRIM28 is implicated in the pathogenesis of glioblastoma by inducing autophagy." (PMID 39534556, 2024). "In glioblastoma, tripartite motif containing 28 (TRIM28) has been identified as a specific marker of stem-like cells, contributing to their invasion." (PMID 39229278, 2024). "TRIM28 knockout inhibits autophagy in glioblastoma cells and increases p21 expression, inducing tumor cell cycle arrest." (PMID 39100077, 2024). "The crosstalk of TRIM28 with transcription factors of stemness in glioblastoma is further explored in a recent study by Porčnik and colleagues." (PMID 36139694, 2022). "We have shown before, on a protein level, that TRIM28 is expressed in glioblastoma tissues and glioblastoma stem cells." (PMID 34500575, 2021). "Taken together, this is the first study to show that TRIM28 is involved in the glioblastoma invasion process in vitro and in vivo." (PMID 34500575, 2021). "miR-491 and Tripartite motif containing 28 (TRIM28) are reported to aberrantly express in glioblastoma multiforme (GBM)." (PMID 27905892, 2016). "Suppression of TRIM28 can impede autophagy in glioblastoma cells." (PMID 39534556, 2024). "Additionally, TRIM28 holds promise as a prospective biomarker for predicting tumor classification in glioblastoma." (PMID 39534556, 2024). "Downregulation of TRIM28 can inhibit the autophagy of glioblastoma cells." (PMID 36756159, 2023). "A recent study demonstrates that TRIM28 is part of a co-repressor complex in glioblastoma." (PMID 36139694, 2022). "The specific anti‐TRIM28 nanobody, NB237, has been demonstrated to significantly inhibit the invasion and metastasis of both glioblastoma cells and glioblastoma stem cells within the zebrafish brain." (PMID 39534556, 2024). "Likewise, substantially higher levels of TRIM28 were observed in XAF1−/− versus XAF1+/+ sublines of HT1376 (bladder) and T98G (glioblastoma) cells." (PMID 39532800, 2024). "Similarly, miR-491 targets TRIM28 in the pathogenesis of glioblastoma multiforme (GBM)." (PMID 36685589, 2022). "Also, over-expression of TRIM28 is associated with poor outcome in GM patients, while TRIM52 controls cell cycle with a reduced proliferation speed and a compromised cycle progression in U87MG and A172 glioblastoma (GBM) cell lines." (PMID 31137886, 2019).
Obesity (16 papers, 2016 to 2026). Accumulation of substantial excess body fat. "Dysregulation of TRIM28 has been linked to a wide range of disorders, including neurodegenerative diseases, autoimmune conditions, and metabolic disorders such as obesity and type 2 diabetes." (PMID 39534556, 2024). "TRIM28 haploinsufficiency has been demonstrated to induce a bistable obesity phenotype in mice, which is linked to the dysregulation of nonclassically imprinted genes." (PMID 39534556, 2024). "With regard to adiposity, it has been demonstrated that mice heterozygous for a global null mutation in the Trim28 gene had a distinct variance in body weight favoring obesity compared with their wild-type littermates." (PMID 33397965, 2021). "Here, the authors demonstrate that adipocyte specific loss of Trim28 in committed adipocytes leads to sex specific differences in the development of obesity, and that this phenotype is associated with altered metabolic flexibility and lipid metabolism." (PMID 33397965, 2021). "Nnat expression has also been associated with a TRIM28-dependent mechanism thought to contribute to the stochastic obesity seen in mice on some genetic backgrounds." (PMID 30279096, 2018). "Hoping for additional mechanistic insight into the obesity decision, we also mapped our RNA-seq reads to a compendium of genomic repeat sequences as TRIM28 has previously been implicated in control of repeat expression." (PMID 26824653, 2016). "Adipose tissue transcriptome analyses in children indicate that humans too cluster into distinct sub-populations, stratifying according to Trim28 expression, transcriptome organization, and obesity-associated imprinted gene dysregulation." (PMID 26824653, 2016). "In support of a causal role for Nnat downregulation in Trim28+/D9-induced obesity and bi-stability, paternal deletion mutants (Nnat+/−p) exhibited a hyper-variable adiposity phenotype, again clearly emerging in adulthood." (PMID 26824653, 2016). "To find causal underpinnings for the obesity induction, we intersected RNA-sequencing datasets comparing epididymal adipose tissue gene expression in our obese- and lean-Trim28+/D9 animals with comparable data contrasting high-fat diet (HFD)-induced obese animals with chow-fed controls (GSE38337)." (PMID 26824653, 2016). "Finally, we demonstrate that deletion of Trim28 leads to loss of expression of the gene Klf14, a well-described sex-specific metabolic regulator, revealing a previously unexplored link between Trim28, Klf14, and the development of obesity." (PMID 33397965, 2021). "Trim28+/D9 offspring (WT for Nnat) showed bi-stable growth trajectories culminating in a bi-stable obesity, whereas solely their Nnat+/-p siblings (WT for Trim28) showed distinct early bifurcating overgrowth trajectories." (PMID 36097183, 2022). "Aging and obesity strengthen TRIM28-dependent epigenetic regulation, such as activating tumor-associated molecular patterns (TAMPs), dampening the farnesoid x receptor (FXR) pathway, over-activating β-catenin, and altering the androgen pathway." (PMID 36100865, 2022). "Trim28 haploinsufficiency has previously been shown to impact the Agouti viable yellow mouse coat color and drive a bimodal obesity phenotype in FVB/NJ mice." (PMID 34668484, 2021). "Trim28 haploinsufficiency has previously been shown to trigger obesity, which is positively correlated with male infertility." (PMID 32302554, 2020). "A dysfunctional imprinted gene network has been associated with an epigenetically regulated bi-model distribution of obesity, triggered by Trim28 haploinsufficiency, in both mice and human." (PMID 32877400, 2020). "It has also been suggested that Nnat forms part of a TRIM28-dependent imprinted gene expression network and that this is involved in the stochastic obesity seen in in-bred mouse strains." (PMID 30279096, 2018).
Obesity (continued). "Global analysis of the two differential obesity datasets revealed low overall correlation (Pearson R = 0.16; Spearman R = 0.11), indicating that the Trim28+/D9-induced obese state is distinct from that induced by over-feeding." (PMID 26824653, 2016). "Preliminary experiments examining maternal HFD effects in Trim28+/D9 animals suggest possible increased obesity rates." (PMID 26824653, 2016). "Documenting many individuals and litters, we observed that the Trim28+/D9-sensitized obesity emerged during a relatively short window in early adulthood (8–12 weeks of age) and then remained stable." (PMID 26824653, 2016). "Non-classical IGN1 dysregulation was one of the strongest signatures distinguishing Trim28+/D9 obesity from HFD-induced obesity in mice and was a predictor of high-dimensional transcriptome variation in childhood adipose tissue." (PMID 26824653, 2016). "Preliminary F1 epistasis examination crossing B6.Nnat+/−p and FVB/NJ.Trim28+/D9 animals has yet to reveal any marked increase in obesity incidence and therefore suggests that Nnat and Trim28 lie in the same genetic pathway." (PMID 26824653, 2016). "However, the present study reveals that mice with adipocyte‐specific TRIM28 deletion also exhibit obesity, similar to the phenotype seen in models with global TRIM28 deletion, suggesting a role for TRIM28 beyond its developmental functions." (PMID 39534556, 2024). "Notably, the obesity phenotype was significantly more evident in female mice, suggesting that TRIM28 acts as a sex‐specific regulator of obesity." (PMID 39534556, 2024). "TRIM28 inhibits the activation of β-catenin triggered by aging and obesity." (PMID 36100865, 2022). "Moreover, we demonstrate that female Trim28 adi-KO mice have an exacerbated obesity phenotype, consistent with the sex-specific effects demonstrated in global models." (PMID 33397965, 2021). "However, in the current study we demonstrate that mice with deletion of Trim28 specifically in committed adipocytes, also develop obesity similar to global Trim28 deletion models, highlighting a post-developmental role for Trim28." (PMID 33397965, 2021). "Most recently, TRIM28 was found to modulate the prevalence of obesity in the population." (PMID 28684781, 2017). "Interestingly, we find that isogenic Trim28+/D9 mutant animals exhibit obesity in an “on/off” manner, emerging into adulthood as either obese or normal, and thus yielding a bi-modal body-weight distribution for the population." (PMID 26824653, 2016). "Because Trim28+/D9 was originally identified as a silencing “E(var)” mutation, we focused on genes downregulated in obese-Trim28+/D9 animals but unaltered or increased in HFD-induced obesity." (PMID 26824653, 2016). "Thus, an IGN1-centric gene signature characterizes Trim28+/D9-induced obesity." (PMID 26824653, 2016). "TRIM28 haploinsufficiency results in a stochastic bi‐stable phenotype, characterized by the development of obesity or an alternative, nonobese state, also known as polyphenism." (PMID 39534556, 2024). "Haploinsufficiency of TRIM28 was shown to trigger a bistable obesity phenotype in mice, which was attributed to non-classical imprinted gene dysregulation." (PMID 32302554, 2020). "Careful examination of these effects revealed a non-random, non-Gaussian hyper-variability in Trim28+/D9 mice, Rather, mutant mice exhibited obesity in an “on/off” manner in isogenic Trim28+/D9 colonies." (PMID 30863426, 2019). "Moreover, SETDB1 and TRIM28 (also known as KAP1), which both repress retrotransposons, also modulate obesity in mice." (PMID 31877125, 2019). "Thus, humans appear to stratify into sub-populations defined by adipose TRIM28 expression, with Trim28_Low individuals exhibiting distinct transcriptional complexity, IGN1 dysregulation, and increased obesity incidence." (PMID 26824653, 2016). "Here, we identify a Trim28-dependent network capable of triggering obesity in a non-Mendelian, “on/off” manner." (PMID 26824653, 2016).
Obesity (continued). "However, neither were Trim28-heterozygous mice in our study presented with obesity nor were such obese mice reported to have impaired fertility." (PMID 32302554, 2020). "Interestingly, this also implies that the observed infertility is not obesity-related but germ cell-autonomous as further supported by germ cell-specific TRIM28 haploinsufficiency." (PMID 32302554, 2020). "Thus, a non-classical imprinted gene signature specifies Trim28+/D9-dependent bi-stable obesity." (PMID 26824653, 2016). "Thus, Trim28+/D9 mice exhibit non-Mendelian bi-stable obesity." (PMID 26824653, 2016). "In particular, the absence of TRIM28 in skeletal muscle, whether during development (MCK–cre) or postdevelopment (ACTA1–cre–ERT2), did not protect against HFD‐induced obesity or glucose intolerance." (PMID 39534556, 2024).
Wilms tumor (13 papers, 2018 to 2025). An embryonal neoplasm characterized by the presence of epithelial, mesenchymal, and blastema components. "TRIM28 mutations have been implicated in approximately 8% of familial and 2% of sporadic cases of Wilms tumor." (PMID 40142302, 2025). "Research has identified several genes associated with Wilms’ tumor predisposition, such as TRIM28, FBXW7, KDM3B, and NYNRIN." (PMID 40142302, 2025). "Analyzing exome sequencing of lymphocyte DNA from Wilms tumor involving 890 individuals has shown that TRIM28, FBXW7, KDM3B, and NYNRIN are new predisposition genes of Wilms tumor." (PMID 38926399, 2024). "Genetic evidence shows loss of TRIM28 gives rise to familiar Wilms tumor, a renal blastoma affecting children, which strongly indicates TRIM28 has a distinct role in kidney malignancy." (PMID 36935008, 2023). "The four new Wilms tumour predisposition genes identified—TRIM28, FBXW7, NYNRIN, and KDM3B—are involved in diverse biological processes and, together with the other 17 known Wilms tumour predisposition genes, account for about 10% of Wilms tumour cases." (PMID 30885698, 2019). "This suggests that TRIM28 mutations make a sizeable contribution to epithelial Wilms tumour, and we recommend that all children with this rare favourable subtype of Wilms tumour should be offered TRIM28 gene testing." (PMID 30885698, 2019). "Familial Wilms tumour pedigrees due to TRIM28 mutations showed incomplete penetrance and a strong parent-of-origin effect, because all inherited mutations were maternally transmitted." (PMID 30885698, 2019). "Our study identified TRIM28 as a major Wilms tumour predisposition gene, making a similar contribution to familial and unselected Wilms tumour as those of constitutional WT1 and REST mutations." (PMID 30885698, 2019). "We identified pathogenic truncating mutations of TRIM28 in 17 individuals with Wilms tumour from 13 families." (PMID 30885698, 2019). "Here we report that mutations of TRIM28, a gene located in proximity of the candidate familial Wilms tumour locus on 19q13.4, are present in the germline in families with Wilms tumours." (PMID 29912901, 2018). "TRIM28, which encodes a transcriptional co-repressor, is located at 19q13.4 in the proximity of a putative familial Wilms tumour locus." (PMID 29912901, 2018). "The clinical behaviour of all five TRIM28-variant tumours supports previous observations that the monomorphic epithelial subtype of Wilms tumour is usually associated with excellent prognosis and presentation with early stage disease." (PMID 29912901, 2018). "Here we report that germline loss of function mutations in TRIM28 predispose children to Wilms tumour." (PMID 29912901, 2018). "Interactions of TRIM28 with other known Wilms tumour-associated proteins raise the possibility of functional links to tumorigenesis." (PMID 29912901, 2018). "However, here we report a child with bilateral Wilms tumour who had inherited a pathogenic TRIM28 variant from their father." (PMID 38282073, 2024). "TRIM28 (Tripartite Motif Containing 28) is a gene that is associated with an autosomal dominant form of inherited Wilms tumor predisposition, which accounts for approximately 8% of familial Wilms tumors and 2% of sporadic Wilms tumors." (PMID 36295546, 2022). "Pathogenic TRIM28 variants identified in nine S1 favorable histology Wilms tumors." (PMID 30543698, 2018). "TRIM28-mutated tumours had a monomorphic epithelial histology that is uncommon for Wilms tumour." (PMID 29912901, 2018). "This might explain why inactivating TRIM28 mutations seem to predispose to Wilms tumour alone." (PMID 30885698, 2019). "TRIM28 has been recently identified as a tumour suppressor in Wilms’ tumour, a common paediatric kidney malignancy (reviewed in72)." (PMID 35906245, 2022). "We recommend that all individuals with Wilms tumour should be offered genetic testing and particularly, those with epithelial Wilms tumour should be offered TRIM28 genetic testing." (PMID 30885698, 2019).
Wilms tumor (continued). "TRIM28 has also been reported to co-immunoprecipitate with AMER1, which is mutated or deleted in 20–30% of Wilms tumours." (PMID 29912901, 2018). "Finally, in family ID_0477, which included six cases of Wilms tumour, we identified TRIM28 929G→A, leading to the protein change Gly310Asp." (PMID 30885698, 2019). "Here, we describe germline mutations and loss of function of TRIM28 in familial Wilms tumours, along with somatic loss of function in a non-familial Wilms tumour." (PMID 29912901, 2018). "In agreement with the lack of TRIM28 protein, the expression of TRIM28 mRNA (probe 200990_at) in 37T and W117 was substantially lower than in the other Wilms tumours, consistent with complete or marked loss of expression." (PMID 29912901, 2018). "Here we report the presence of truncating germline variants, somatic mutation, and epigenetic silencing of TRIM28, in familial and non-familial cases of Wilms tumour." (PMID 29912901, 2018). "The most common mechanisms of WT predisposition include 11p15-related WT (Beckwith-Wiedemann spectrum), WT1 disorder, REST-related WT, TRIM28-related WT, and WAGR (Wilms tumor, aniridia, genitourinary anomalies, range of developmental delays) spectrum." (PMID 36743884, 2023). "The mechanisms underlying this Wilms tumour predisposition are not known, but it is notable that TRIM28 is a major binding partner of AMER1, which is encoded by a gene that is frequently somatically mutated in Wilms tumour." (PMID 30885698, 2019). "Critically, these tumours were negative for TRIM28 immunohistochemical staining whereas the epithelial component in normal tissue and other Wilms tumours stained positively." (PMID 29912901, 2018).